ABCG2 (ATP binding cassette subfamily G member 2 (JR blood group))
Diseases named in the same sentence as ABCG2 in open-access papers (continued):
Sharing a sentence is not in itself a finding about the gene and the disease.
colon carcinoma (continued). "However, studies comparing the expression of ABCG2 mRNA in normal colon tissue and tumor tissue showed that primary colon cancer cells exhibit an initial downregulation of ABCG2 mRNA expression." (PMID 33261018, 2020). "Furthermore, TMP195 also reversed ABCG2-mediated resistance to mitoxantrone, a known drug substrate of ABCG2, in S1-M1-80, an ABCG2-overexpressing MDR variant of S1 human colon cancer cells, and in HEK293 cells transfected with human ABCG2 (R482)." (PMID 31905792, 2019). "We also showed that ABCG1 and ABCG2 were co-expressed in the metastatic colon cancer cells." (PMID 30364132, 2018). "Together, these results suggest that ALDH1 and ABCG2 may be used as biochemical markers in diagnosis and prognosis of colon cancer." (PMID 31516883, 2018). "Finally, tumor cells isolated from 13 surgically resected colon tumors and propagated as solid tumor spheroids in vitro have been shown to possess stem cell properties including self-renewal, expression of ABCG2, and resistance to SN-38." (PMID 28880238, 2017). "To confirm whether the blockage of ABCG2 could increase the effect of PDT in colon cancer, we tested the cell survival rate and singlet oxygen production." (PMID 26149077, 2015). "To confirm ABCG2 effect in PDT, we tested ABCG2 expression level in colon cancer cell lines." (PMID 26149077, 2015). "Our data showed that ABCG2 overexpression strongly induced photosensitizer efflux which means that ABCG2 inhibition may be the solution of drug resistance in colon cancer." (PMID 26149077, 2015). "The aim of this study was to see whether ABCG2 is a target protein in enhancing colon cancer PDT efficacy." (PMID 26149077, 2015). "Our studies demonstrate that PDT efficacy is regulated by ABCG2 expression level in colon cancer." (PMID 26149077, 2015). "However, we directly showed ABCG2 effect in colon cancer cell using ABCG2 overexpressed cell line both in vitro and in vivo, providing direct evidences of enhanced PDT effect when inhibiting the ABCG2." (PMID 26149077, 2015). "In this study, we hypothesized that ABCG2 is a target protein in enhancing colon cancer PDT efficacy." (PMID 26149077, 2015). "However, the molecular mechanism of controlling ABCG2 expression in drug resistance of colon cancer is unclear and scarcely reported." (PMID 22870247, 2012). "All of these results suggest that the JNK1/c-jun signal pathway is involved in expression of the ABCG2 gene in colon cancer cells, and may contribute to chemoresistance." (PMID 22870247, 2012). "Actually, our result demonstrated that constitutive overexpression of ABCG2 in drug-resistant colon cancer cells SW1116/HCPT resulted in great resistance to chemotherapeutic drugs, although the underlying molecular mechanisms remained unknown in detail." (PMID 22870247, 2012). "However, the relationship of JNK activation and ABCG2 expression is scarcely studied, particularly in colon cancer cells." (PMID 22870247, 2012). "Importantly, ABCG2 was found to confer resistance to doxorubicin in breast, ovarian and colon cancer cell lines." (PMID 18382425, 2008). "Moreover, our immunofluorescence results showed a statistical correlation of 79% for the co-localization of PMI and ABCG2, suggesting that PMI may play a role in the treatment of colon cancer using LBP by modulating ABCG2." (PMID 38576495, 2024). "Complementary to this, human colon cancer cell lines may also express other efflux transporters, such as ABCG2 (breast cancer resistance protein, BCRP), ABCC3 (multidrug resistance-associated protein 3, MRP3) and ABCC2 (multidrug resistance-associated protein, MRP2)." (PMID 36983038, 2023). "Moreover, they revealed that the diminished expression of miR-203 in CRC led to the alleviation of DNMT3B repression, resulting in the methylation of the ABCG2 promoter and a significant decrease in ABCG2 expression observed in both colon cancer cell lines and patient-derived CRC specimens." (PMID 37705098, 2023).
colon carcinoma (continued). "Indeed, low levels of the negative Notch regulator miR-34a were associated with a worse response of colon cancer patients to 5-FU, and its overexpression overcame ABCG2-mediated resistance of a stem cell-like subpopulation of colon cancer cells to 5-FU through downregulation of DLL1/Notch signaling." (PMID 34680255, 2021). "Therefore, in this study, we determined the in vitro efficacy of cariprazine to reverse resistance to the anticancer drug, mitoxantrone, an ABCG2 substrate, mediated by the overexpression of ABCG2 transporters in non-small lung cancer cells and colon cancer cells." (PMID 30181510, 2018). "A previous study has investigated the relationships between ABCG2, ABCC1, and ABCB1 genes in two different colon cancer cell lines (Caco-2 and HT-29)." (PMID 41557172, 2026). "Immunohistochemistry revealed the PMI, ABCG2, PI3K, and AKT protein expression levels in each xenografted colon cancer model mouse group." (PMID 38576495, 2024). "In the present study, LBP combined with oxaliplatin simultaneously inhibited the expression of PMI and ABCG2 and also confirmed the important role of PMI in the process of drug resistance in colon cancer." (PMID 38576495, 2024). "The combination of ABCG2 and TOP1 gene expression significantly divided the stage III colon cancer patients enrolled in PETACC-3 into two groups regarding benefit from adjuvant treatment with FOLFIRI." (PMID 35996085, 2022). "The increased expression of ATP-binding cassette (ABC) transporter genes such as ABCB1, ABCC1, and ABCG2, as other CSC-related characteristic is involved in regulation of self-renewal and multidrug resistance in ovarian and colon cancer cell lines." (PMID 33849536, 2021). "In recent literature, ABCG2 co-expressed with lncRNA CTD-2589M5.4 similarly changed in both of the multidrug resistant ovarian cancer cell lines and colon cancer cell lines." (PMID 34454479, 2021). "It was also suggested that the expression level of ABCG2 and ABCB5 decreased following c-myc silencing and sensitized colon cancer stem cells to chemotherapy." (PMID 34536148, 2021). "It should be noted that the RF values for the S1-M1-80 colon cancer cells lines for mitoxantrone and SN-38 were significantly greater than for the HEK293 cells transfected with the ABCG2 gene." (PMID 33158067, 2020). "This study shows that the combination of ABCG2 and TOP1 gene expression significantly divided the Stage III colon cancer patients into two groups regarding benefit from adjuvant treatment with FOLFIRI but not 5FUL." (PMID 32326511, 2020). "In these experiments, we determined the reversal effect of poziotinib on the efficacy of specific anticancer drugs in colon cancer cells overexpressing the ABCG2 or ABCB1 transporters and in HEK293 cells transfected with the ABCG2 or ABCB1 gene." (PMID 33158067, 2020). "In recent publications, we correlated each of ABCG2 and TOP1 mRNA expression to patient outcome in a subset of Stage III colon cancer patients enrolled in the PETACC-3 study." (PMID 32326511, 2020). "Our results indicate that by decreasing the MDR1, MRP1, and ABCG2 drug transporters, AR inhibitor fidarestat increases the sensitivity of DOX to colon cancer by decreasing the efflux of drugs from the cells." (PMID 28600556, 2017). "More recently, we published data on ABCG2 mRNA expression and benefit (DFS and OS) in stage III colon cancer patients receiving an adjuvant combination of 5-FU or 5-FU plus irinotecan." (PMID 28880238, 2017). "No genomic insertions, deletion, or rearrangements were detected in ABCG2+/ABCB5+ LESCs; however, genetic abnormalities were detected in SW620 colon cancer cells." (PMID 29230251, 2017). "We have recently reported that vatalanib, an orally active small molecule multi-tyrosine kinase inhibitor, can sensitize multidrug resistant (MDR) colon cancer cells to chemotherapy under hypoxia by inhibiting two MDR transporters ABCB1 and ABCG2." (PMID 27014726, 2016).
colon carcinoma (continued). "In this aspect, our research suggests a very important role of ABCG2 in drug resistance and PDT efficacy in colon cancer cell, and provides reasonable and sufficient evidence to develop ABCG2 inhibitor for protecting drug resistance." (PMID 26149077, 2015). "However, the association ABCG2 and PDT efficacy in colon cancer cell remain unclear." (PMID 26149077, 2015). "It has been found in mitoxantrone (MX) selected colon cancer cell line S1-M1-80, hence giving ABCG2 the name of mitoxantrone resistant protein (MXR)." (PMID 25268163, 2014). "Below, the results of our studies demonstrate that inhibition of the JNK pathway is able to down-regulate ABCG2 and the JNK pathway can be exploited for overcoming ABCG2-mediated multidrug resistance in colon cancer." (PMID 22870247, 2012). "With these minds, we focused on the expression linkage between ABCG2 and the involvement of JNK/c-Jun in the HCPT-resistant colon cancer cell subline SW1116/HCPT." (PMID 22870247, 2012). "In the hydroxycamptothecin (HCPT) resistant cell line SW1116/HCPT from human colon cancer cell line SW1116, ABCG2 is the major factor for multidrug resistance, other than well-studied ABCB1 or ABCC1." (PMID 22870247, 2012). "The phenylfurocoumarin derivative (R)-9-(3,4-dimethoxyphenyl)-4-((3,3-dimethyloxiran-2-yl)methoxy)-7H-furo [3,2-g]chromen-7-one (PFC) in HCT-116/BCRP colon cancer cells, drastically lowers the IC50 of SN-38 while inhibiting ABCG2/BCRP-mediated drug transport function." (PMID 38572428, 2024). "Interestingly, ABCG1 and ABCG2 are co-expressed in metastatic colon cancer cells, with ABCG1 influencing ABCG2 expression through the modulation of HIF-1α." (PMID 39850800, 2024). "In summary, this study confirmed that LBP combined with oxaliplatin plays a role in reversing drug resistance in colon cancer cells by down-regulating the PMI/PI3K/AKT pathway and simultaneously inhibiting the expression of ABCG2+ colon cancer stem cells to promote apoptosis." (PMID 38576495, 2024). "Despite the thorough database search and the data supporting the expression of ABCC3 and ABCG2 in colon cancer cells, no expression of these transporters was detected in our Colo 320 samples." (PMID 36839907, 2023). "In contrast, ensartinib was equally cytotoxic to the ABCG2-overexpressing human S1-MI-80 colon cancer cells and the ABCG2-overexpressing H460-MX20 human non-small-cell lung cancer (NSCLC) cells as to the parental S1 and NCI-H460 cancer cells." (PMID 35565470, 2022). "Consequently, we used an immunofluorescence assay to determine if poziotinib altered the membrane localization of the ABCG2 and ABCB1 transporters in drug-resistant S1-M1-80 and SW620/Ad300 colon cancer cells, respectively." (PMID 33158067, 2020). "However, it should be pointed out that the ABCG2 and ABCB1 ATPase was expressed in High Five insect cells, whereas the effects of poziotinib on the resistance to the anticancer drugs were done in colon cancer cells." (PMID 33158067, 2020). "As previously reported, [3H]-mitoxantrone accumulation was significantly lower in the ABCG2 overexpressing S1-M1-80, compared to the S1 (non-drug resistant) colon cancer cells." (PMID 33158067, 2020). "Importantly, two key genes in apoptosis and stemness, BCL2 and ABCG2, were also upregulated in EP300-knockout colon carcinoma cells and their paclitaxel-resistant derivatives." (PMID 28341962, 2017). "In human colon cancers, it is not fully examined the role of ABCG2 in porphyrin-based photodynamic therapy." (PMID 26149077, 2015). "In colon cancer cells, HT29 cell showed the highest expression of ABCG2 mRNA and protein." (PMID 26149077, 2015). "Almost all previously studies were focus on P-glycoprotein-mediated multidrug resistance, but the relationship of JNK signal pathway and ABCG2 transporters is not reported in colon cancer cells." (PMID 22870247, 2012).
colon carcinoma (continued). "Similarly to observations reported in colon cancer cells, we found inhibition of the MAPK/ERK signalling pathway by MEK1/2-specific inhibitor U0126 to reduce SP, possibly through altering ABCG2 expression or localisation." (PMID 23226356, 2012). "Interestingly, it has been reported that decreasing expression of ABCG2 and ABCB5 may induce the depletion of c-Myc and enhance the chemosensitivity of colon cancer stem cells (CSCs)." (PMID 34381520, 2021). "The assay was performed with a parental HT29 colon cancer cell line (HT29par) and a HT29 colon cancer cell line made resistant to SN-38 (HT29SN38), of which the latter has previously been shown to be upregulated in the ABCG2 gene and to be overexpressing ABCG2/BCRP." (PMID 34680166, 2021). "Poziotinib (0.6 μM) and Ko143 (0.6 μM), an ABCG2 inhibitor, significantly increased the intracellular accumulation of [3H]-mitoxantrone, a substrate for the ABCG2 transporter, in the S1-M1-80 colon cancer cells but did not significantly affect accumulation on the S1 parental cells." (PMID 33158067, 2020). "Moreover, results showed that protein expression of ABCG2 was elevated in colon cancer tissues compared with non-cancerous tissues." (PMID 31516883, 2018). "The expression levels of ALDH1 and ABCG2 in cancer tissues as well as in benign tumor samples were determined by immunohistochemistry using tumor tissues microarray of TNM (Tumor, Node, Metastasis) in 42 patients with colon cancer samples as well as in 18 corresponding benign tumors." (PMID 31516883, 2018). "Notably, we observed that PXR controls the expression of genes that were previously reported to confer CSC chemoresistance or to have a negative impact on disease-free survival in colon cancer patients, including ABCG2, ABCC6, ALDH1A1, CYP3A4, or S100A10." (PMID 27448961, 2016). "In addition, it was shown that AhR activation in colon cancer cells induces expression of multiple target genes including matrix metalloproteinase (MMP)-9, calcium ion flux, pro-inflammatory IL-1β and the drug transporter BCRP/ABCG2." (PMID 26264025, 2015). "The limited sensitivity of colon tumor cells to porphyrins may not necessarily be a result of white light application, but mainly drug resistance inducement by ATP-binding cassette subfamily G2 (ABCG2) proteins." (PMID 35335367, 2022). "In contrast, in vitro, 5 μM of VKNG-2 did not significantly alter either the expression of ABCG2, AKT, and PI3K p110β protein or the subcellular localization of the ABCG2 protein compared to colon cancer cells incubated with the vehicle." (PMID 33671108, 2021). "Thus, CPT11 resistance might be related to the SCC population and ABCG2 expression, whereas CVV showed dose-dependent responses regardless of the SCC population, suggesting that our CVV might overcome drug resistance originating from the stem cell-like colon cancer cell population." (PMID 26918725, 2016). "An alteration in the membrane localization of the ABCG2 and ABCB1 transporters (i.e., the transporters would not be located in the cell cytoplasmic membrane and thus can not efflux the anticancer drugs from the colon cancer cells) could decrease the resistance to the anticancer drugs." (PMID 33158067, 2020).
ovarian carcinoma (95 papers, 2009 to 2026). A malignant neoplasm originating from the surface ovarian epithelium. "ABCG2 is involved in topotecan resistance in ovarian cancer, which is associated with miR-212-3p downregulation." (PMID 38539161, 2024). "CD109-overexpressed A2780 cells showed an increase in ABCB1 and ABCG2 protein expression levels, which are associated with drug resistance and the poor prognosis of ovarian cancer." (PMID 37373457, 2023). "Several studies have investigated the relationship between ABCG2 genotype variants with ovarian cancer outcome." (PMID 35582032, 2021). "ABCG2 was induced in patients after their chemotherapy, and also by estrogens in the PA-1 ovarian cancer cell line after stable transfection with the gene encoding ERα." (PMID 28674494, 2017). "Polymorphism p.Gln141Lys in the ABCG2 gene, borderline significant (OR 0.64; 95% CI 0.40-1.02; p = 0.059), decreased the risk of ovarian cancer for heterozygotes." (PMID 25591549, 2015). "Accordingly, CD133+CXCR4+ OVCAR5 sorted cells were evaluated for sensitivity to cisplatin, a commonly used agent for the treatment of ovarian cancer, and for the expression of ABCG2, a surface transporter associated with resistance to chemotherapy." (PMID 26020117, 2015). "Ovarian cancer stem cells, through selective carriers such as ABCG2 and MDR1, are known to be a major cause of tolerance to chemotherapy, metastasis, and recurrence of ovarian cancer." (PMID 23067401, 2012). "High ABCC2 and ABCG2 expressions were associated with increased PFS in all ovarian cancer subtypes." (PMID 35582032, 2021). "Also, in heterozygotes for ABCG2 polymorphism p.Gln141Lys we found a trend towards decreased risk of ovarian cancer." (PMID 25591549, 2015). "Because SIK3 functions have been reported to be associated with glucose tolerance/energy metabolism 31,32, further studies may be needed to our current observation, identify the regulation of ABCG2 in EOC as well as glycolytic activity/metabolic change in SIK3-associated ovarian cancer." (PMID 31762812, 2019). "Independent studies have confirmed high expression of ABCB1 in paclitaxel-resistant ovarian cancer cells and ABCG2 in topotecan-resistant cells." (PMID 41303640, 2025). "The expression of PPARγ/ABCG2 was correlated to chemoresistance in ovarian cancer clinical specimens as well." (PMID 40709184, 2025). "For example, increased expressions of ABCC1 and ABCG2 reduced the therapeutic effect in an ovarian cancer cell line." (PMID 39457707, 2024). "The expression of most genes involved in iron export, including ABCG2, FLVCR1, FLVCR2, and SLC40A1, was associated with improved PFS in ovarian cancer." (PMID 38186569, 2023). "There are limited studies targeting the ABCG2 gene for ovarian cancer, even though it is being studied clinically in other cancers; however, there is a correlation between ABCG2 upregulation and resistance to anthracyclines, such as doxorubicin." (PMID 36551731, 2022). "While it was initially isolated from a breast cancer cell line, increased expression of ABCG2 has been identified in many cancers, including myeloma, glioblastoma, esophageal, tongue, and ovarian cancer." (PMID 36551731, 2022). "In ovarian cancer, overexpression of ABCG2 has been revealed through elevated mRNA transcript levels in topotecan-resistant A2780 and IGROV1 cells." (PMID 36551731, 2022). "As a result, additional research into miRNA-induced ABCB1 or ABCG2 expression, which results in ovarian cancer drug resistance, will aid in our knowledge of the mechanism of drug resistance of ABC transporters." (PMID 35799305, 2022). "Another study challenged ovarian cancer cell lines with six different chemotherapies and found increased ABCG2 mRNA expression in vincristine- (P < 0.01) and topotecan-resistant (P < 0.001) cell lines." (PMID 35582032, 2021).